TWIST1 (twist family bHLH transcription factor 1)
Diseases named in the same sentence as TWIST1 in open-access papers (continued):
Sharing a sentence is not in itself a finding about the gene and the disease.
cancer (continued). "The basic helix-loop-helix transcription factor Twist1 has well-documented roles in progenitor populations of the developing embryo, including endocardial cushions (ECC) and limb buds, and also in cancer." (PMID 25262113, 2014). "Transcription factors of the Twist family (Twist1, Twist2), snail family (SNAI1/snail, SNAI2/slug), as well as ZEB family (ZEB1, ZEB2), control the EMT process in cancer." (PMID 24244294, 2013). "Taken together, these data show that TWIST1 regulates and maintains IL8 expression in breast epithelial and cancer cells." (PMID 22891766, 2012). "Collectively, these data demonstrate that TWIST1-induced IL8 production regulates the invasive properties of breast epithelial and cancer cells through an autocrine loop." (PMID 22891766, 2012). "The regulatory outcome is more complex since in cancer cells, HIF-1α can bind the TWIST1 promoter directly and control its expression." (PMID 22942713, 2012). "Here we show that TWIST1 induces the production of interleukin 8 (IL8), which activates matrix metalloproteinases and promotes invasion of breast epithelial and cancer cells." (PMID 22891766, 2012). "Twist1 is a major regulator of EMT and it has also been identified as capable of promoting carcinoma metastasis." (PMID 22245869, 2012). "Together these studies provide accumulating evidence that Twist1 coordinately regulates multiple downstream target genes to promote cell migration in ECC mesenchymal cells, as well as in other embryonic and cancer cell types." (PMID 22242143, 2011). "TWIST1 activates EMT in the context of embryonic morphogenesis, tissue fibrosis and cancer metastasis." (PMID 20646316, 2010). "Twist1 is a principal transcription factor, that triggers embryonic development and cancer cell behaviors such as EMT, cell migration, and invasion, influencing cancer cell activities through various cellular pathways." (PMID 40003882, 2025). "MDA‐MB‐231 cells were treated with CNa 29 to determine whether pharmacological inhibition of calpain 2 by CNa 29 prevents filamin A cleavage‐induced HIF1α nuclear translocation, TWIST1 expression, EMT, cancer stemness, and metastasis." (PMID 40151834, 2025). "TWIST1 induced transcriptional regulation promotes EMT and neural crest migration by upregulating N-cadherin and suppressing E-cadherin, a process similarly hijacked in cancer metastasis." (PMID 40831499, 2025). "Similarly, Twist1 siRNA can reverse the high expression of EMT markers induced by adriamycin, and the anti-cancer efficacy in combination with adriamycin is significantly better than that of monotherapy." (PMID 41211430, 2025). "We analyzed a group of genes that were upregulated in MSC lines compared to cancer cell lines, including transcription factors (ZBTB16, HAND2, and TWIST1), a cadherin regulating cell adhesion (CDH20), a receptor tyrosine kinase (PDGFR-α), and a negative cell cycle regulator (CDKN2A)." (PMID 39621192, 2025). "TWIST1/2 regulate genes involved in EMT promotion and cancer metastasis." (PMID 40361472, 2025). "Specifically, the mEVs from CRC patients caused an increase in the expression of TWIST1 and VIM (protein name: vimentin) in all the studied cancer cell lines, while those from healthy subjects did not." (PMID 39764464, 2024). "Hence, Snail and Twist1 are crucial proteins that influence EMT and cancer stem cell (CSC) formation, two processes that have much overlap and lead to heightened cancer aggression and metastasis." (PMID 39000112, 2024). "In this study, only a few stemness genes, such as SOX2, TWIST1, and CD34, were aberrantly expressed [absolute fold change (FC) ≥ 2] in more than five cancer types, indicating that integrins may function downstream of key stemness factors." (PMID 39436262, 2024).
cancer (continued). "In conclusion, the present work documented the ability of harmine to exert multiple anti-cancer actions on ATC cells, being able to revert the EMT by reducing the expression of Twist1; and to impair ATC cell proliferation, motility, anchorage-independent growth and, in one ATC cell line, survival." (PMID 38256193, 2024). "Several transcription factors (TFs) mediate the development of EMT, including SNAIL1/SNAIL2, TWIST1/TWIST2 and ZEB1/ZEB2, which are overexpressed in various carcinomas along with the under expression of the metastasis suppressor Raf Kinase Inhibitor Protein (RKIP)." (PMID 39335152, 2024). "Snail/Slug, TWIST1, and Zeb1/2 are classical EMT-TFs that bestow cancer stem cell features." (PMID 38139368, 2023). "TWIST1 and EMT can have a great impact on the response of cancer cells to a wide variety of drugs." (PMID 38139368, 2023). "Similarly, TWIST1 has a pronounced effect on cancer progression by enhancing EMT, stimulating the proliferation and invasiveness of cancer cells, and promoting metastasis and resistance to chemotherapy." (PMID 37762215, 2023). "Twist1 is more commonly expressed in gastric CAFs than in those of other cancer species and is rarely expressed in non-cancerous tissues." (PMID 37143134, 2023). "Furthermore, we restored the expression of TWIST1 and STC1 in LNMAS overexpressed cells and determined their effects on cancer cells metastasis and macrophage phagocytosis, respectively." (PMID 35152264, 2022). "Taken together, these results suggest that MAP2K2, LUM, RPS6, PDCD4, TWIST1, and HIF1A may play important roles in DMD pathophysiology by regulating the MAPK pathway and proteoglycans in cancer." (PMID 36619896, 2022). "FOXE1, TWIST1 and other hyper-methylated genes involved in cell cycle regulation were observed in PDAC cancers, thus suggesting that their down-regulation may encourage uncontrolled cell proliferation in PDAC." (PMID 36329447, 2022). "In our proposed DMD-related lncRNA-mRNA pathway networks, PYCARD, RIPK2, and CASP1 were significantly enriched in the NOD-like receptor signaling pathway, whereas MAP2K2, LUM, RPS6, PDCD4, TWIST1, and HIF1A were significantly enriched in proteoglycans in cancers." (PMID 36619896, 2022). "In addition to NANOG, Twist1 and Bmi1 are important factors in the promotion of EMT and are positively correlated with poor prognosis in various cancers." (PMID 36114703, 2022). "In a later study OPN from cancer cells was found to stimulate the CAF myofibroblastic phenotype via ERK and Akt pathways that induced Twist1-dependent gene expression, leading to CXCL12 secretion, which ultimately promoted epithelial-to-mesenchymal transition (EMT) in cancer cells." (PMID 35378690, 2022). "Similar to Snail, Twist1 represses the epithelial marks such as E‐cadherin, α‐catenin, γ‐catenin and upregulates mesenchymal marks including vimentin, fibronectin, N‐cadherin, leading to EMT and cancer progression." (PMID 35601657, 2022). "The mechanisms underlying the interaction between TCF4 and TWIST1 and the role of the TCF4–TWIST1 complex in cancer cachexia have not been investigated." (PMID 35406121, 2022). "Similarly, no significant expression changes were observed in the studied mesenchymal markers in the resistant cancer cells such CDH2, VIM, ZEB1, ZEB2, SLUG, TWIST1 that which are upregulated in completed EMT." (PMID 35523936, 2022). "EMT is also associated with invasion in new tissues, supported by the upregulation of Snail Family Transcriptional Repressor 1 (SNAI1) and Twist Basic Helix-Loop-Helix Transcription Factor 1 (TWIST1) via Snail Family Transcriptional Repressor 2 (SLUG; SNAI2) regulation in different cancer types." (PMID 35574343, 2022). "Thus, TWIST1 represents a considerable therapeutic target for the suppression of esophageal cell transformation to CSCs and to abolish ESCC recurrence after cancer therapy." (PMID 36474162, 2022).
cancer (continued). "Whether triptonide directly binds to Twist1 and Notch1 proteins in TNBC and other cancer cells remains to be determined." (PMID 34922602, 2021). "We next used the KTC1 and PDX.008.CL cell lines, as well as the metastatic patient sample to quantify copy number and expression of several cancer-related genes located on chromosome 7p and 7q, including RAC1 (7p22.1) TWIST1 (7p21.1), EGFR1 (7p11.2), MET (7q31.2) and BRAF (7q.34)." (PMID 34638434, 2021). "ZEB1, ZEB2, SNAI1, and TWIST1 drive EMT of cancer cells, but they are not required for metastasis in animal models." (PMID 34339740, 2021). "Moreover, FBXO45 inhibited cancer development and metastasis by targeting EMT-inducing transcription factors, including SNAI1/2, TWIST1/2, and ZEB1/2, in various cancer cells." (PMID 33966034, 2021). "In conclusion, ADQ successfully suppressed carcinogenic activity by inhibiting the Akt signaling pathway and Twist1, which suggests that ADQ may be an efficient candidate for cancer drug development." (PMID 34408201, 2021). "By implication, Twist1 activity is insufficient to induce cancer cell invasion and distant metastasis in the absence of Slug, making it an attractive therapeutic target." (PMID 34868979, 2021). "In cancer cells, EMT-induced signals may be the results of EMT-transcription factors, including ZEB1 and TWIST1." (PMID 34885101, 2021). "We found that cancer cells overexpress epithelial-to-mesenchymal transition markers TWIST1 and SNAI2, as well as stem-like marker CD44 (but not CD133, SOX2 and/or NANOG)." (PMID 33531664, 2021). "Chemotherapy increases the expression of Twist1 and several ATP-binding cassette transporters in invasive cancer cells, but not in non-invasive cells." (PMID 33768509, 2021). "TWIST1, EMT-promoting transcription factor, is an essential for cancer metastasis." (PMID 33917757, 2021). "In addition, analysis of the Cancer Cell 2010 dataset showed that TMPRSS4 expression was significantly correlated with expression of SOX2 (rho = 0.484, P = 3.48e-10) and TWIST1 (rho = 0.368, P = 3.491e-06)." (PMID 34809669, 2021). "Additionally, HMGA2 increases the expression of cancer stem cell markers, including CD44, Oct4, and Twist1." (PMID 33668453, 2021). "CTCs with the expression of mesenchymal markers, like TWIST1, SNAIL1, or vimentin were more likely to be identified in patients with advanced cancer compared to those with early-stage cancer, suggesting the potential role in metastatic dissemination and disease progression." (PMID 34150608, 2021). "We speculate that Twist1-induced genome instability potentially drives EMT and therefore cancer progression." (PMID 32337580, 2020). "Therefore, markers of EMT, such as vimentin, FN1, twist family bHLH transcription factor 1 (TWIST1), snail family transcriptional repressor 1 (SNAI1) and 2 (SNAI2, best known as SLUG) can be used to detect cancer dormancy." (PMID 33193295, 2020). "Additionally, no other similar phosphatases were able to constitute this reaction with the same efficiency, and the inverse concentration of TWIST1 and CTDSP1 has been observed in several cancer cell lines." (PMID 32397221, 2020). "Conditioned media derived from MYC/Twist1- but not MYC-HCC cells was sufficient to promote the migration of macrophages towards cancer cells." (PMID 31933479, 2020). "Western blotting further revealed that overexpressing miR-22 decreased Twist1 protein levels, but not snail levels which has been reported the miR-22-target in other cancer cell lines." (PMID 32391253, 2020). "The role of Twist1 is well established in EMT during early development and cancer progression." (PMID 32337580, 2020). "Moreover, in 33 different human cancers, expression of both MYC and TWIST1 predict survival, expression of CCL2/IL13 and M2-like TAM infiltration." (PMID 31933479, 2020). "Furthermore, FOXQ1 has been shown to be a regulator of cancer invasion and metastasis in CRC and a modulator of Twist1 expression." (PMID 33330033, 2020).
cancer (continued). "Twist1 is a member of the basic helix-loop-helix transcription factor family and is an important transcription factor that induces EMT, migration and invasion in cancer cells." (PMID 31941509, 2020). "Furthermore, Twist1 expression positively correlates with EMT genes (CDH1, OCLN, TJP1, CDH2, FN1, SNAI1 and VIM) in various cancers." (PMID 32337580, 2020). "Another phenotype induced by YAP/TAZ and relevant for cancer biology is epithelial-to-mesenchymal transition (EMT), which may be further reinforced by ECM stiffness owing to the direct regulation of Twist1 nuclear localization." (PMID 31963820, 2020). "MYC and TWIST1 predict poor prognosis, TAM infiltration and pro-TAM cytokines in 33 human cancers." (PMID 31933479, 2020). "The TWIST1 promoter is methylated in cancer, although this did not correlate with low TWIST1 RNA or protein levels." (PMID 33298572, 2020). "Correlation of MYC+TWIST1 expression with CCL2 and IL13 in TCGA pan-cancer cohort (n = 9502)." (PMID 31933479, 2020). "Thus, MYC and TWIST1 predict poor survival, CCL2/IL13 expression and M2-like TAM infiltration in human cancers." (PMID 31933479, 2020). "TWIST1 can act as a predictor of distant metastasis, plays an important role in the progression of OSCC during the EMT process, and is also involved in the later stage of cancer development." (PMID 32104177, 2020). "Finally, in non-small lung carcinoma, PRMT1 methylates TWIST1 and induces EMT related aggressive cancer behavior." (PMID 31655611, 2019). "Here we report that the HIV-1 Tat-interacting protein 60 kDa (Tip60) acetyltransferase mediates acetylation at lysine residues of SPZ1 at positions 369 and 374, and of TWIST1 at positions 73 and 76, which are required for SPZ1–TWIST1 complex formation and cancer cell migration in vitro and in vivo." (PMID 30154425, 2019). "Hence, we also analysed the VPA effect on nuclear protein levels of Twist1 and Snail1, two transcription factors crucial for mesodermal differentiation in embryos and for the induction of EMT in cancers." (PMID 30373123, 2018). "Twist2, which shares more than 90% identity with Twist1, also promotes EMT in human cancers." (PMID 29685144, 2018). "Another phenomenon we observed is that, in NANOGP8 over-expressed cancer cells, expression of EMT signature genes such as TWIST1, PRRX1, ZEB, Vimentin, and N-caderin, was significantly up-regulates and expression of the epithelial marker E-caderin was reversely down-regulated." (PMID 29689047, 2018). "While Twist1 promotes cancer metastasis, the current study demonstrates that SNCG knockdown is able to inhibit the promotion of cancer metastasis by Twist1, suggesting that SNCG may be a pro-metastatic effector downstream of Twist1." (PMID 29795373, 2018). "Cancer database and molecular analyses revealed that it activates Wnt/β-catenin signaling axis, as evident by enhanced nuclear localization and function of β-catenin marked by increased level of SNAIL1, SNAIL2, ZEB1, and TWIST1 and its downstream gene targets." (PMID 29748568, 2018). "A mesenchymal phenotype, characterised by low expression of E-cadherin (CDH1), high expression of vimentin (VIM) and high expression of EMT-inducing transcription factors, such as TWIST1, ZEB1, SNAI1 and SNAI2 moreover correlates with the expression of cancer stem cell markers CD44 and CD90." (PMID 29299154, 2017). "Twist1 and Zeb1 immunohistochemistry was performed using FFPE tissues of PTC, but no increase in the expression of Twist1 and Zeb1 at the invasive border was observed as compared with the corresponding cancer centre." (PMID 28489070, 2017). "Hence, we analyzed the nuclear protein levels of Twist1 and Snail1, two transcription factors important for mesodermal differentiation in embryos and for the induction of EMT in cancers." (PMID 28081224, 2017). "Moreover, the co-expression of Twist1 and CAF markers was examined in individual cancer-stromal fibroblasts of five ESCC tissue samples using confocal microscopy." (PMID 29029429, 2017).
cancer (continued). "TNF-α could induce Twist1 expression and overexpression of Twist1 could promote further metastasis, which increased the expression of MMP-9, MMP-2, CD44v6 and vimentin in cancer cells." (PMID 28774312, 2017). "Herein, we demonstrate that EMT-TFs Twist1, Snail1 and Six1 influence neighbouring carcinoma cells in a non-cell autonomous (NCA) manner, by increasing EMT features and aggressive properties of cells not expressing these TFs." (PMID 28604738, 2017). "Most of these miRNAs repressed cancer cell EMT and metastasis in most examined cancer types, and some of them (miR-33a and miR-186) modulated cancer cell sensitivity to cisplatin by down-regulating TWIST1." (PMID 27930738, 2016). "EMT transcription factors Zeb1, Snail and Twist1 are important players in the regulation of EMT during cancer metastasis through different signaling cascades, including the Akt, Erk1/2 and signal transducer and activator of transcription 3 (STAT3) signaling pathways." (PMID 27121055, 2016). "Twist1, acting as a repressor of E-cadherin, induces EMT and endows cells with the enhanced migratory and invasive capabilities necessary for metastasis, which is one of the most important processes in cancer progression." (PMID 27121312, 2016). "Moreover, invasive phenotypes and stemness properties can be uncoupled in carcinomas, since ZEB1 and TWIST1 exhibit a dose‐dependent role in malignant progression." (PMID 27596438, 2016). "Although studying the functional role of EMT proteins is not within the scope of this study, previous studies demonstrated that TWIST1 and ZEB2 have other roles including repressing cellular senescence and conferring stem-like properties to cancer cells respectively." (PMID 26214683, 2015). "We show that in the presence of N-cadherin expressing cancer cells metformin inhibits TWIST1/N-Cadherin/NF-kappaB signaling independent of AMPK." (PMID 26359363, 2015). "Twist1 was methylated in 40% of intramucosal cancers, while the frequency of methylation in non-cancerous gastric mucosae including atypical foci was rare (10%), indicating that Twist1 methylation is an early event in DGC carcinogenesis in our mouse model." (PMID 26695186, 2015). "The upstream or downstream signaling pathways of Twist1 are not completely understood, although there is supportive information that Twist1 is upregulated by classical EMT-inducing pathways during development, inflammation, and cancer." (PMID 26360779, 2015). "Nevertheless, there are a lot of findings that DNA methylation at the Twist1 promoter region is not correlated with expression of the gene in various cancers." (PMID 26695186, 2015). "In our study, we have found the promoter region of TWIST1 gene in MDA-MB-435 and HeLa cancer cell lines are highly hypermethylated, and TQ treatment did not make any change in methylation level of TWIST1 promoter in these two cell lines." (PMID 26023736, 2015). "Therefore, our results identify mechanism by which BRMS1 attenuates cancer cell progression through downregulating HIF-1α and subsequently reducing Snail and TWIST1 expression." (PMID 26520789, 2015). "ATF3 up-regulates the genes TWIST1, fibronectin (FN)-1, SNAIL and SLUG in MCF10A cancer cells." (PMID 26537518, 2015). "TWIST1 and TWIST2 expression in stroma were significantly positively correlated in low-grade (r = 0.41) and to a lesser extent in high-grade (r = 0.26) budding cancers." (PMID 25528769, 2015). "Twist1, the basic helix-loop-helix domain-containing transcription factor, is involved in the process of EMT and has been demonstrated to play a key role in the metastatic progression of human cancer." (PMID 26538215, 2015).